RNU6-897P (RNA, U6 small nuclear 897, pseudogene)
Gene: Small nuclear RNA gene on chromosome 6 (104,766,822 to 104,766,926, forward strand). Ensembl gene ENSG00000252944.
Homologues: Orthologues: chimpanzee U6 (98% identical), macaque U6 (62% identical). Paralogues in human: RNU6-38P (74% identical), RNU6-1145P (73% identical), RNU6-658P (73% identical), RNU6-1011P (72% identical), RNU6-1322P (72% identical), RNU6-242P (72% identical), RNU6-468P (72% identical), RNU6-48P (72% identical), RNU6-698P (72% identical), RNU6-83P (72% identical), RNU6-85P (72% identical), RNU6-1175P (71% identical), and 1283 more.